MYL3 (myosin light chain 3)
Diseases named in the same sentence as MYL3 in open-access papers (continued):
Sharing a sentence is not in itself a finding about the gene and the disease.
virus infection (1 paper, 2025). "However, the role of MYL3 in virus infection remains undiscovered." (PMID 40560751, 2025). "Combining MYL3 and IGF1R inhibitors might offer a synergistic approach to prevent viral infection." (PMID 40560751, 2025).
cardiac disease (5 papers, 2015 to 2024). "Cardiac troponin I and myosin light chain 3 demonstrated strain- and sex-specific elevations in the acute phase with subsequent decline despite ongoing progression of cardiac disease." (PMID 31263061, 2019). "Both Myl3 and Actc1 were included by KEGG in the circulatory pathways ASC and CMC, and also in HCM and DIL cardiac disease pathways." (PMID 38534766, 2024).
tumor (5 papers, 2012 to 2025). "Our results indicate that the molecules involved in this pathway (MSN and MYL3) are either upregulated or downregulated in the margin and center, which suggests the importance of agranulocyte adhesion in both parts of the tumor." (PMID 35512017, 2022). "It is of interest that both molecules involved in AJs, MYL3 and TUBB, are upregulated in the tumor center, which may be important for AJs in this region." (PMID 35512017, 2022). "The tumor center was characterized by a higher abundance of LMNA (two proteoforms), dihydropyriminidase-related protein (DPYSL3), tubulin beta (TUBB), myosin light chain 3 (MYL3), and galectin-1 (LGALS1)." (PMID 35512017, 2022). "Notably, MYL3 and DYPSL3 were upregulated in the tumor center, which strongly suggests the importance of these proteins in the center’s characteristics." (PMID 35512017, 2022). "Although the genes in (PRKAA2, GNG7, MYL3, NOS1, ADCY1, PLCB1, MYLK3, and MYLK4) the apelin/APJ signaling axis are found to be downregulated and might not be considered responsible in cdRCC progression, downregulation of GNG7 tells a different story due to its tumor‐suppressive activity." (PMID 40304310, 2025).
cancer (2 papers, 2023 to 2024). A tumor composed of atypical neoplastic, often pleomorphic cells that invade other tissues. "Regarding the remaining DEPs, Myh4, Acta1, Tnnt3, Mb, Ttn, Actn2, Myh7, Myl1, Mybpc2, Myl3, and Tnnc2 are associated with several cancers." (PMID 39861068, 2024).
cardiovascular disease (2 papers, 2024 to 2025). "We selected 2 proteins, MYL3 and cysteine and glycine-rich protein 3 (CSRP3), which are abundantly expressed in hearts and are closely associated with cardiovascular diseases, for further investigation." (PMID 40007621, 2025).
infection (1 paper, 2025). The state of being infected such as from the introduction of a foreign agent such as serum, vaccine, antigenic substance or organism. "Consistent with GO based findings, the KEGG pathways analysis also revealed downregulation of contractile genes such as TNNT2 and MYL3, reinforcing infection-induced disruption of the muscular apparatus." (PMID 40943072, 2025).
metabolic disease (1 paper, 2017). A congenital disorder (due to inherited enzyme abnormality) or acquired (due to failure of a metabolically important organ) disorder resulting from an abnormal metabolic process. "Most of these P/LP variants were found in validated minor sarcomere genes (ACTC1, MYL2 and MYL3) and genes related to metabolic diseases (GLA and PRKAG2)." (PMID 28771489, 2017).
MYL3 also shares sentences with these, for which no sentence is quoted: acute myocardial infarction (2 papers); familial hypertrophic cardiomyopathy (2); heart failure (2); myopathies (2); asymmetrical septal hypertrophy (1); atrial fibrillation (1); breast carcinoma (1); colorectal cancer (1); Danon disease (1); depression (1); entropion (1); hypertrophy (1); medulloblastoma (1); muscular disease (1); myelofibrosis (1); neurodevelopmental disorder (1); neuromuscular disease (1); restrictive cardiomyopathy (1); sarcopenia (1); schizophrenia (1); spinal muscular atrophy (1); squamous cell carcinoma (1); Wolff-Parkinson-White syndrome (1).